NEGR1 (neuronal growth regulator 1)
Diseases named in the same sentence as NEGR1 in open-access papers (continued):
Sharing a sentence is not in itself a finding about the gene and the disease.
depression (continued). "In this study, we investigated whether NEGR1 deficiency alters gut microbiota composition and whether these changes are linked to neuronal atrophy and anxiety- and depression-like behaviors in Negr1 KO mice." (PMID 40388597, 2025). "Notably, NEGR1 (rs1432639), a neuronal growth regulator known to associate with migraine, depression and seizures, the significant phi coefficients were negative for males and positive for females." (PMID 39696186, 2024). "By integrating GWAS, brain expression quantitative trait loci data, and transcriptome-wide association studies, the association was confirmed and assigned the highest probability of causality; increased abundance of NEGR1 was significantly associated with an increased depression risk." (PMID 37895235, 2023). "However, it is likely that NEGR1 is regulating pathways that are linked with depression and, therefore, its role in the reactivity to escitalopram deserves further studies." (PMID 36552158, 2022). "In the initial GWAS of the AFFECT mood disorders, we identified several genome-wide significant loci; the strongest association was between MD and SNPs within NEGR1, a gene encoding a synaptic adhesion protein that has been robustly associated with depression in prior studies." (PMID 35338122, 2022). "The neuronal growth regulator 1 (encoded by the gene Negr1) and the limbic system-associated membrane protein (encoded by Lsamp) have been shown to be expressed in the hypothalamus and to be involved in anxiety and depression-like behavior regulation." (PMID 36498834, 2022). "Importantly, NEGR1 has also been linked to other psychiatric disorders, such as schizophrenia, depression, and Alzheimer’s disease, as well as human intelligence and dyslexia." (PMID 34828381, 2021). "In accordance with the initially described role of NEGR1 in the brain, polymorphisms in NEGR1 have emerged among the most robust associations across different psychiatric disorders, including autism spectrum disorder, major depression, and schizophrenia." (PMID 34572334, 2021). "The strongest GWAS associations, however, have linked NEGR1 with depression." (PMID 34572334, 2021). "The Negr1 gene has been significantly associated with major depression in genetic studies." (PMID 32751911, 2020). "We have previously demonstrated that Negr1 knockout (KO) mice exhibited depression- and anxiety-like behaviors." (PMID 40698360, 2025). "alleviates anxiety- and depression-like behaviors in Negr1 KO mice, potentially by inducing neuronal morphological changes in the NAc and DG." (PMID 40388597, 2025). "Remarkably, daily administration of an Akkermansia strain isolated from wild-type mice reversed the neuronal structural abnormalities and ameliorated anxiety- and depression-like behaviors in Negr1 KO mice." (PMID 40388597, 2025). "In human genetic studies, the rs10789336 in NEGR1 was correlated with the expression levels of RPL31P12 in brain tissue and an increased risk of major depressive disorder." (PMID 40405979, 2025). "Over-expression of NEGR1, a synapse-adhesion gene highlighted by psychiatric GWAS, induces depression-like behaviour and impairs myelination; knocking it down rescues stress-induced anhedonia, revealing a fresh therapeutic target for synaptic repair." (PMID 41373485, 2025). "isolated from WT mice not only alleviated anxiety- and depression-like behaviors in Negr1 KO mice but also restored impaired dendritic arborization and spine density." (PMID 40388597, 2025). "Among the five IgLON family members, both NEGR1 and OPCML have been linked to major depressive disorder, schizophrenia, autism, anorexia nervosa, and Alzheimer’s disease." (PMID 38540422, 2024). "We have delineated the epigenetic mechanism by which the gain of AP1AR-DT in mice induces depression and anxiety-like behaviors by reducing Negr1-mediated excitatory synaptic transmission." (PMID 39558356, 2024).
depression (continued). "We observed that Negr1-RE ameliorated depression-like behaviors in AP1AR-DTOE mice, as evidenced by reduced immobility time in the TST and FST as compared to the AP1AR-DTOE mice." (PMID 39558356, 2024). "In human studies, rs10789336 in NEGR1 was associated with expression levels of RPL31P12 in brain tissues, and with the risk for major depressive disorder, implying shared genetic liability between mood disorders and cardiovascular disease risk." (PMID 38420755, 2024). "Additional support to NEGR1 contribution to this disorder derived from a study uncovering a potential impact in the comorbidity with major depression in multiple sclerosis patients." (PMID 37895235, 2023). "Three of these genes (NEGR1, TMEM106B, HNF1A) have been linked to each of the three diseases (CAD, T2D and depression) in previous studies, supporting their probable involvement in psycho-cardiometabolic multimorbidity." (PMID 37390107, 2023). "Recently, NEGR1 has been indicated among the principal players in the genetic correlations between obesity and a number of psychiatric disorders, including major depression, schizophrenia, and anorexia nervosa." (PMID 37895235, 2023). "Although the linkage between NEGR1 and depression is the strongest, evidence also suggests the involvement of NEGR1 in a wide spectrum of psychiatric conditions." (PMID 36552158, 2022). "In fact, in terms of major depression, transcriptome-wide association research analyses of major depression indicated significant correlations with the expression of DRD2 in the nucleus accumbens (NAc) and NEGR1 in the hypothalamus, among others." (PMID 36294858, 2022). "These included established loci in psychiatric genetics, such as NEGR1 with depression (P = 2.15 × 10−9) as well as RERE and FURIN with schizophrenia (P = 4.43 × 10−6 and P = 1.05 × 10−7, respectively)." (PMID 33481009, 2021). "In the large GWAS studies, NEGR1 gene has been one of the most significant gene loci for both body mass phenotype and depression." (PMID 34572334, 2021). "The aim of this study was to assess if different antidepressant treatments affected the expression of Negr1 and other genes belonging to the same pathway in rodent depression models." (PMID 32751911, 2020). "Recent functional and genomic studies implicate the role of NEGR1 in a wide spectrum of psychiatric disorders, such as major depression, schizophrenia and autism." (PMID 30932003, 2019). "However, female Negr1-/- mice exhibit greater vulnerability to fear learning impairments and depression-like behavior, whereas males Negr1-/- mice show heightened anxiety responses." (PMID 41588420, 2026). "Our findings highlight the importance of considering sex as a biological variable in depression research and suggest that Negr1 plays a crucial role in the sex-specific pathophysiology of psychiatric disorders through complex mechanisms spanning central and peripheral systems." (PMID 41588420, 2026). "is associated with anxiety- and depression-like behaviors and abnormalities in neuronal cell morphology in Negr1 KO mice, we administrated a single strain (m3-2) of the Akkermansia isolates or PBS to Negr1 KO and WT mice every weekday for 4 wk." (PMID 40388597, 2025). "In this study, we investigated the gut microbiota in Negr1 knockout (KO) mice, which exhibit anxiety- and depression-like behaviors, as NEGR1 (neuronal growth regulator 1) is a cell adhesion molecule linked to neuronal development and neuropsychiatric disorders." (PMID 40388597, 2025). "NEGR1 (ENSG00000172260; chr1:71,395,943–72,282,539; GRCh38) encodes neuronal growth regulator 1, a synaptic adhesion molecule that has been implicated in human major depressive disorder in several studies." (PMID 39558356, 2024). "Also, Negr1 has been proposed as a biomarker of major depression because CSF Negr1 levels were elevated in patients with this disorder." (PMID 38370417, 2024).
depression (continued). "It is questionable if Negr1−/− mice represent an appropriate model for depression despite the strong link of the human NEGR1 gene with depression phenotypes in accumulating studies because higher levels of NEGR1 have been described in the tissues and body fluids of depressed patients." (PMID 36552158, 2022). "The most recent data from depression patients suggest that the functional impact of NEGR1 might involve systemic regulation of homeostasis, as significant upregulation of NEGR1 has been shown in the hypothalamus and peripheral blood of depression patients." (PMID 34572334, 2021). "The genes that are potentially of interest for the study of depression include the Neural Growth Regulator 1 (NEGR1), the glutamate metabotropic receptor 5 (GRM5), the glutamate ionotropic receptor kainate type subunit 3 (GRIK3) and the transmembrane protein 106B (TMEM106B) protein coding genes." (PMID 29662059, 2018). "As a known physical interaction partner of Negr1, Cntn1, an immunoglobulin superfamily member, has been previously shown to increase in the hippocampus following chronic unpredictable stress, where its upregulation correlates with anxiety- and depression-like behaviors." (PMID 41440084, 2025). "may contribute to the development of anxiety- and depression-like behaviors of Negr1 KO mice." (PMID 40388597, 2025). "Given that NEGR1 is considered one of the major etiological factors of multiple mental illnesses, including major depressive disorder and autism, our findings may provide new insight into understanding the role of NEGR1 and IL-6 during the development of these neuropathological symptoms." (PMID 37187893, 2023). "In the bivariate meta-analyses of the broad depression phenotype and self-reported MDD, three loci (NEGR1, MAT2B, MUC21) reached genome-wide significance and all were replicated." (PMID 30626913, 2020). "The two IgLON family members NEGR1 and OPCML share common links with several of them, such as schizophrenia, autism, and major depressive disorder." (PMID 38540422, 2024). "NEGR1 supports neuron growth and synaptic flexibility in feeding–reward circuits, while its expression is reduced in the hypothalamus of obese individuals and in the prefrontal cortex (PFC) of patients with depression." (PMID 41375608, 2025). "In a comprehensive meta-analysis of depression, recent GWAS involving millions of participants have identified common comorbidities with SUD, highlighting crucial correlations with the expression of NEGR1 in the hypothalamus and DRD2 in the NAc." (PMID 39635461, 2024). "We investigated whether antidepressants modulate the expression of genes belonging to Negr1-Fgfr2 pathway in Flinders sensitive line (FSL) rats, in a corticosterone-treated mouse model of depression, and in mouse primary neurons." (PMID 32751911, 2020). "Interestingly, increased cerebrospinal fluid protein levels of NEGR1 were found in major depressive disorder and bipolar disease but not schizophrenia compared to controls." (PMID 29479305, 2018). "Individual genes that commonly emerge among these studies include those with existing links to depression, such as DRD2 and FADS1, as well as novel genes such as NEGR1 and RPL31P12 without existing links to depression." (PMID 37076454, 2023).
schizophrenia (13 papers, 2015 to 2025). A major psychotic disorder characterized by abnormalities in the perception or expression of reality. "Based on Gwas meta-analysis from the Psychiatry Genomics Consortium, there is strongest evidence for the association of OPCML and NEGR1 genes with schizophrenia, compared to other IgLONs." (PMID 29434535, 2018). "Significantly, elevated levels of NEGR1 transcripts were found in the dorsolateral prefrontal cortex of patients with schizophrenia compared to healthy controls." (PMID 32373164, 2020). "Growing evidence suggests that the IgLON family of neural adhesion molecules LSAMP, NTM, NEGR1, and OPCML are important candidates in forming the susceptibility to schizophrenia (SCZ)." (PMID 29434535, 2018). "According to the Kruskal–Wallis test, there was a statistically significant difference in NEGR1 protein level between the control group and the two subgroups of schizophrenia patients (H2 = 8.01, df = 2, p = 0.01)." (PMID 29434535, 2018). "Alteration of Negr1 expression has been described in two other neurological disorders characterized by marked connectivity dysfunctions, namely dyslexia and schizophrenia, suggesting that Negr1 plays pivotal role in the establishment of a functional wiring." (PMID 26793057, 2015). "Furthermore, a series of GWAS have revealed NEGR1 as a causal risk factor for ASD, schizophrenia, and Alzheimer’s disease." (PMID 40698360, 2025). "Post hoc comparisons using Tamhane’s test indicated that the mean NEGR1 protein expression score of schizophrenia patients with the paranoid subtype diagnosis (m = 1.72, sd = 0.43) was statistically higher than the mean score of controls (m = 1.24, sd = 0.24, p < 0.05)." (PMID 29434535, 2018). "Additionally, the mean NEGR1 protein expression score of schizophrenia patients with another subtype diagnosis (m = 1.93, sd = 0.57) was statistically higher than the mean score of controls (m = 1.24, sd = 0.24, p < 0.05)." (PMID 29434535, 2018). "Furthermore, Lsamp and NEGR1 proteins are significantly upregulated in the post-mortem anterior prefrontal cortex of the patients with schizophrenia compared to healthy controls." (PMID 29434535, 2018). "According to the model, the log of the odds of being a schizophrenia patient was positively related to the expression levels of NTM 1b and NEGR1 (in both cases p < 0.05)." (PMID 29434535, 2018). "We detected significantly elevated levels of the NEGR1 transcript (1.33-fold increase) and the NTM 1b isoform transcript (1.47-fold increase) in the DLPFC of schizophrenia patients compared to healthy controls." (PMID 29434535, 2018).
Anxiety (10 papers, 2018 to 2026). Intense feelings of nervousness, tension, or panic often arise in response to interpersonal stresses. "Negr1 deficiency also leads to an anxiety- and depression-like state in mice and is accompanied by reduced adult neurogenesis and excitatory synaptic function, which is consistent with our observation in mice with gain of AP1AR-DT." (PMID 39558356, 2024). "More recently, Negr1-deficient mice exhibited both anxiety- and depressive-behaviors as well as a reduction in miniature EPSC frequency in DG granule cells." (PMID 39558356, 2024). "Overall, Negr1 deficiency disrupted typical behavioral adaptations to social stress, with males showing impaired physiological recovery and females displaying enhanced anxiety-like traits." (PMID 41440084, 2025). "Female Negr1-/- mice displayed impaired fear learning and increased depression-like behavior, while male Negr1-/- mice exhibited heightened anxiety-like responses." (PMID 41588420, 2026). "Behaviorally, Negr1-/- mice showed increased anxiety-like behavior, decreased social interaction, and impaired spatial learning in the Morris water maze, regardless of sex." (PMID 41588420, 2026). "Male Negr1−/− mice showed impaired adaptation in weight regulation and locomotor activity, while Negr1−/− females displayed heightened anxiety-like behavior and reduced stress-induced hyperactivity." (PMID 41440084, 2025). "Our findings illustrate an epigenetic mechanism by which the gain of bipolar disorder-associated upregulated AP1AR-DT in mice induces depressive and anxiety-like behaviors by reducing Negr1-mediated excitatory synaptic transmission." (PMID 39558356, 2024). "Taken together, these results suggest that depressive- and anxiety-like behaviors in AP1AR-DTOE mice can be attenuated by normalizing the excitatory synaptic transmission of mPFC neurons through restoring of the Negr1 activity." (PMID 39558356, 2024). "NEGR1 regulates neural growth, connectivity, and cognitive functions and has been reported as a genetic risk gene for MDD and other comorbid disorders such as anxiety and autism." (PMID 40301990, 2025). "We then validated the function of the DE-lncRNA AP1AR-DT in a mouse model and revealed the regulatory molecular mechanism by which the overexpression of AP1AR-DT in mice induces depressive and anxiety-like behaviors by reducing Negr1-mediated excitatory synaptic transmission." (PMID 39558356, 2024). "This revealed the epigenetic mechanism by which the gain of bipolar disorder-associated upregulated AP1AR-DT in mice induces depressive and anxiety-like behaviors by reducing Negr1-mediated excitatory synaptic transmission, providing an etiological implication for bipolar disorder." (PMID 39558356, 2024). "Moreover, the overexpression of recombinant Negr1 in AP1AR-DTOE mice resulted in the amelioration of anxiety- and depressive-like behaviors as well as the normalization of the reduced excitatory synaptic transmission induced by the gain of AP1AR-DT." (PMID 39558356, 2024). "Finally, we subjected Negr1-KO mice to various behavioral tasks to evaluate overall activity, anxiety, sensorimotor gating, social interaction, cognitive performance and seizure susceptibility." (PMID 29479305, 2018). "We further demonstrated that overexpression of recombinant Negr1 in the mPFC neurons of AP1AR-DTOE mice ameliorates depressive and anxiety-like behaviors and normalizes the reduced excitatory synaptic transmission induced by the gain of AP1AR-DT." (PMID 39558356, 2024).
autism (10 papers, 2015 to 2025). Persistent deficits in social interaction and communication and interaction as well as a markedly restricted repertoire of activity and interest as well as repetitive patterns of behavior. "A possible relevance of NEGR1 in autism is supported by the observation that NEGR1 downregulation in mice reproduces brain development abnormalities resembling the cortical disorganization of neurons and abnormalities in dendritic spines characterising autism spectrum disorder features." (PMID 37895235, 2023). "Independent genetic studies have linked both Negr1 and FGFR2 to autism." (PMID 26793057, 2015).
Intellectual disability (5 papers, 2018 to 2024). "The NEGR1 gene, specifically on 1p31, has been linked to intellectual disability and learning difficulties as it affects neuronal growth, proliferation, and differentiation." (PMID 39156404, 2024). "More recently, genetic variants in or near the NEGR1 locus have been associated with cognitive disorders including psychiatric disease, intellectual disability and learning difficulties." (PMID 29479305, 2018). "Outside the realm of neuropsychiatric disorders, NEGR1 has been implicated in other diseases whose mechanisms may have a bearing on cognitive and intellectual disabilities that often denote neurodegenerative disorders." (PMID 37895235, 2023). "Another patient affected by microdeletion 1p31, including NEGR1, showed moderate intellectual disability." (PMID 37895235, 2023). "Other neurological phenotypes possibly related to altered NEGR1 function comprise intellectual disability and language impairment, dyslexia and juvenile myoclonic epilepsy." (PMID 29479305, 2018).
diabetes (4 papers, 2020 to 2025). "Using Metascape, we found that 4 genes (AZGP1, DLK1, GCKR and NEGR1) are linked to diabetes." (PMID 38184718, 2024). "The NEGR1 gene, along with TDH and FAM167A-AS1, also associated with impaired fasting glucose and diabetes, respectively, at a slightly lower, yet still significant p-values." (PMID 31888951, 2020).